MIR891A (microRNA 891a)
Synonyms: hsa-mir-891a; MIRN891A
Gene: MicroRNA gene on chromosome X (146,027,794 to 146,027,872, reverse strand). Ensembl gene ENSG00000216056.
Gene Ontology:
Biological process: miRNA-mediated post-transcriptional gene silencing